KIF20A (kinesin family member 20A)
Diseases named in the same sentence as KIF20A in open-access papers (continued):
Sharing a sentence is not in itself a finding about the gene and the disease.
tumor (continued). "Knockdown of either Gli2 or KIF20A significantly reduced tumor volume and weight." (PMID 27036048, 2016). "Despite this procedure, it is assumed that the intensity of CTL induction and the efficacy of vaccine treatment are not necessarily correlated according to a linear function, possibly due to the high expression levels of MHC Class I and/or targeted antigen KIF20A in tumor cells." (PMID 24237633, 2013). "Therefore, the slower growth rate of these tumor cells might be attributed to their tendency for becoming post-mitotic cells due to the half dosage of Kif20a expression, which eventually leads to fewer proliferating cells in the population." (PMID 33976373, 2021). "Moreover, KIF20A expression appears to promote the proliferation and invasion of tumor cells." (PMID 33232285, 2020). "Hence, KIF20A potentially serve as a useful tumor and prognosis marker." (PMID 33232285, 2020). "Taken together, KIF20A may be an important factor in tumor cell proliferation and invasion." (PMID 31565099, 2019). "Knockdown of KIF20A could significantly decrease tumor weight." (PMID 30105795, 2018). "Finally, the subcutaneous xenograft model further identified that KIF20A could promote tumor growth in vivo, consistent with the in vitro result." (PMID 30105795, 2018). "Moreover, assessing tumor expression of KIF20A may improve prognostication and help to identify patients who may benefit from more aggressive treatment." (PMID 28081138, 2017). "In addition, recent studies suggest that KIF20A is involved in tumor progression and angiogenesis." (PMID 27941992, 2016). "Genetic depletion or pharmacological inhibition of KIF20A impairs BCSC viability and tumor initiation and development in vitro and in vivo." (PMID 41392981, 2025). "IFI27, KIF20A, KLK10, and TOP2A were highly expressed in tumor cells, supporting their potential as prognostic biomarkers in PAAD." (PMID 41008826, 2025). "Consequently, we propose a novel hypothesis: KIF20A may function as a “proliferation-immunity evasion switch” in tumor cells, where its expression level determines whether tumor progression is predominantly driven by accelerated proliferation or immune suppression." (PMID 41267030, 2025). "Consistently, KIF20A depletion also resulted in impaired TNBC tumor growth, which resulted in reduced tumor weight and smaller size of xenografts at necropsy." (PMID 41392981, 2025). "By controlling microtubule dynamics and cell division, the protein KIF20A (Kinesin Family Member 20A) plays a crucial role in HCC proliferation and tumor growth by facilitating chromosomal movement during cell division." (PMID 40465746, 2025). "In summary, these studies collectively establish a clear link between tumor progression and three kinesin genes (KIF4A, KIF20A, and KIF11)." (PMID 41462522, 2025). "The analysis results showed that the expression levels of G6PD, KIF20A, NDRG1, RECQL4, and MCM4 were significantly higher in HCC tumor tissues than in normal tissues, while ADH1C was significantly downregulated in HCC tumor tissues." (PMID 41169384, 2025). "To confirm the on-target effect of KIF20A sgRNAs on BCSC initiation in vivo, we carried out tumor initiating assay with limiting dilutions by re-expressing sgRNA-resistant KIF20A in KIF20A-depleted cells (sg1)." (PMID 41392981, 2025). "While PCR validation on matched tumor/normal tissues confirmed significant differential expression of IFI27, KIF20A, KLK10, and TOP2A." (PMID 41008826, 2025). "Therapeutically, KIF20A inhibition with paprotrain suppressed BCSC self-renewal, tumor initiation, and tumor growth in TNBC, as well as sensitized TNBC to standard chemotherapy." (PMID 41392981, 2025). "In an exploratory analysis, expression of KIF20A, CT45, and LY6K as measured by IHC was correlated to clinical features to identify a potential prognostic or tumor biological relevance of the TAA in EOC." (PMID 36768616, 2023).
tumor (continued). "The other five top-rated CTAs CT45, IMP3, KIF20A, PRAME, and SP17 were similarly promising, and reached 8.07 points, due to a lower tier in “Expression on tumor Stem Cells”." (PMID 36768616, 2023). "Six of them (KIF4A, ASPM, KIF20A, KIF14, TPX2, KIF18B) are overexpressed by more than 10-fold in tumor samples and four of them (KIF11, AURKB, TPX2 and KIFC1) are essential for cell survival." (PMID 37835564, 2023). "Six of them (KIF4A, ASPM, KIF20A, KIF14, TPX2, KIF18B) warrant particular attention as they show increased expression by more than 10-fold in tumor samples compared to normal tissues." (PMID 37835564, 2023). "KIF20A and GALNT2 were elevated, whereas GRIA1 expressions were suppressed in tumor tissues, compared with adjacent normal tissues." (PMID 36524130, 2022). "Three identified candidate genes, FADS2, KIF20A, and G6PD, were highly expressed in LUAD tissues and their high expression correlated with poor patient prognosis, and tumor stage." (PMID 36225575, 2022). "In the TCGA dataset, mRNA levels of four genes (CNIH1, KIF20A, GALNT2, and AP3S1) were highly expressed in tumor tissues, while GRIA1 levels were downregulated in tumor tissues." (PMID 36524130, 2022). "As evidenced by IHC staining, the expression levels of KIF20A, MMP-2, MMP-9 and MKI67 increased significantly in tumor tissues in the KDELR2 overexpression group." (PMID 36096734, 2022). "Apart from GRIA1, upregulated mRNA levels of CNIH1, KIF20A, GALNT2, and AP3S1 were observed in tumor tissues in these datasets." (PMID 36524130, 2022). "The protein expression of CD44, HK3, KIF20A, and IDUA was higher in the tumor tissues compared to the normal tissue, and the protein expression of GALM and TGFA was lower in tumor tissues than normal, which was consistent with our results in TCGA." (PMID 33816274, 2021). "The results showed that the mRNA expression levels of hub genes (PBK, KIF2C, NUF2, KIF20A, RAD51AP1 and DEPDC1) in tumor samples (EAC, ESCC) were significantly higher than in normal samples (P < 0.05)." (PMID 33403046, 2021). "For tumor stage, significant differences among stage 1, stage 2, and stage 3 were shown in NDC80, CCNB1, KIF20A, DTL, and TOP2A of the key genes from Jia Liver data set (P < 0.05)." (PMID 34746301, 2021). "Compared with normal kidney tissues, antibody stainings for ANKZF1, CD44, IDUA, KIF20A, PLOD2, and VCAN were high in ccRCC tumor tissues, whereas they were low for CHST6, HS6ST2, NDST3 and FBP1." (PMID 33836688, 2021). "KIF20A is one of the leading edge genes found on GSEA of M1-poly versus M0-NM DEGs and is homologous to KIF2B, a protein that directly promotes tumor metastasis in cell line models of CIN." (PMID 32380981, 2020). "All 6 KIFs selected by LASSO regression were seen overexpressed in tumor samples comparing to normal samples (KIF10, KIF15, KIF18B, KIF4A: P < 0.0001; KIF18A: P = 0.0003; KIF20A: P = 0.0022), which in accordance with bioinformatics results." (PMID 32322170, 2020). "For example, the expression of KIF20A, UCK2, and SLC41A3 should be determined in a larger cohort of HCC cell lines with different phenotypes to demonstrate a putative relationship with tumor aggressiveness." (PMID 32382568, 2020). "In this study, we employed the bioinformatics analysis to identify the upregulation of KIF20A in LUAD, then verified the results in human tumor specimens and LUAD cell lines." (PMID 30105795, 2018). "The results suggested that the expression of KIF20A in LUAD were related to age, gender, lymph node metastasis status, and tumor stage." (PMID 30105795, 2018). "KIF20A was significantly overexpressed at both the mRNA and protein levels in NPC cell lines and human tumor tissues." (PMID 28081138, 2017).
tumor (continued). "The present analysis showed, for the first time, that the anti-tumor effect of fisetin was mediated mainly through activation of CDKN1A, SEMA3E, GADD45B and GADD45A and down-regulation of TOP2A, KIF20A, CCNB2 and CCNB1 genes." (PMID 28052097, 2017). "KIF20A mRNA and protein expression were significantly upregulated in the six NPC tumor samples compared to the three normal nasopharyngeal tissues." (PMID 28081138, 2017). "Here, we report the identification of kinesin family member 20A (KIF20A) as a novel downstream target of Gli2, which is important for HCC proliferation and tumor growth." (PMID 27036048, 2016). "Univariate Cox regression analysis revealed that clinical variables, including upregulation of KIF20A protein (P < 0.001), PLNM (P < 0.001), SCC-Ag (P = 0.003), and tumor recurrence (P < 0.001) were significantly correlated with OS." (PMID 27941992, 2016). "The HLA-A2 (A*02:01)-restricted CTL epitopes of KIF20A were identified using HLA-A2 transgenic mice (Tgm) and the peptides were examined to check whether they could generate human CTLs exhibiting cytotoxic responses against KIF20A+, HLA-A2+ tumour cells in vitro." (PMID 21179034, 2011). "After describing the individual roles of the ferroptosis-related genes (G6PD, KIF20A, EZH2, NT5DC2, SLC7A11), it is essential to investigate how these genes might interact with each other to influence the tumor microenvironment (TME) in a synergistic manner." (PMID 40465746, 2025). "KIF20A is essential to BCSC survival in vivo and TNBC tumor development." (PMID 41392981, 2025). "Our analysis supported three kinesin genes (KIF4A, KIF20A, and KIF11) that may play a key role in tumor initiation and progression by regulating cell proliferation and division." (PMID 41462522, 2025). "Notably, when PCA was repeated using only the six prognostic genes (AQP4, CDCA3, HJURP, KIF20A, PLK1, UHRF1), tumour and normal samples remained partially separable." (PMID 41007424, 2025). "KIF20A expression positively correlates with CD4+ T cell infiltration and may suppress anti-tumor immunity by activating Treg cells." (PMID 41267030, 2025). "Pharmacological inhibition of KIF20A decreases BCSCs and suppresses TNBC tumor growth." (PMID 41392981, 2025). "Given that tumor progression is not solely driven by CSCs and that non-CSCs can also promote tumor progression, we investigated the effect of KIF20A on the proliferation of non-BCSCs." (PMID 41392981, 2025). "Notably, pharmacologic inhibition of KIF20A, which reduces BCSC fitness, sensitized TNBC tumor models to standard chemotherapy." (PMID 41392981, 2025). "In summary, transcriptomic profiling of BCSCs versus non-BCSCs revealed KIF20A to be essential for sustaining abilities of self-renewal, population expansion, and tumor initiation of BCSCs." (PMID 41392981, 2025). "To examine whether KIF20A is sufficient to drive BCSC expansion and tumor progression, we overexpressed KIF20A in MDA-MB-231 and HCC1806 cells." (PMID 41392981, 2025). "The increased presence of this protein could induce the expression of Cyclin F and kinesin family member 20A (KIF20A) proteins as well as the activation of the ERK1/2 and c-Jun N-terminal kinases (JNK)-MAPK signaling pathways in tumor cells." (PMID 39697630, 2024). "Furthermore, a meta-analysis identified KIF20A and ASPM among the top 55 overexpressed genes when comparing tumor and normal samples across the ten most frequent human cancers." (PMID 37835564, 2023). "After the detection of hub genes utilizing the PPI network of common upregulated genes, the top five hub genes, including AURKA, AURKB, KIF20A, MELK, and TTK that played the most critical role in both primary tumor cell and P7731 cell line, were selected to validate the study." (PMID 37231064, 2023). "Increased KIF20A expression has been observed in mouse HCC models and could promote tumor proliferation." (PMID 38170006, 2023).
tumor (continued). "Additionally, overexpression of KIF20A resulted in an increased tumor growth, which also reversed KDELR2 silence-induced decreased tumor growth." (PMID 36096734, 2022). "The two types of tumor cells displayed comparable 4N DNA contents in cell cycle analysis, suggesting that deletion of Kif20a in SHH-MB cells did not alter the cytokinesis status." (PMID 33976373, 2021). "Since FOXM1 and KIF20A are consistently over-expressed in docetaxel-resistant PCa cells and tumor tissues, we explored whether FOXM1 contributed to docetaxel resistance by regulating KIF20A transcription and expression." (PMID 33292277, 2020). "This led to the selection of seven antigens found to be overexpressed in both mouse MM tumor lines under investigation and that were nearly absent in all other mouse normal tissues: KIF20A, KIF2C, MMP9, MNDA, OLFML2B, TROAP, and ULBP1." (PMID 31428586, 2019). "KIF20A was significantly elevated in tumor tissue compared with normal prostate tissue at both the mRNA and the protein level." (PMID 31565099, 2019). "The in vitro results revealed that knockdown of KIF20A could drastically attenuate LUAD cells proliferation and induce tumor cells apoptosis." (PMID 30105795, 2018). "Similarly, depletion of KIF20A in another TNBC line, HCC1806, led to a reduction in CSC frequency (1:3,448 in KIF20A-KO vs. 1:604 in control group, P = 0.00944), accompanied by smaller tumor volumes especially in the 5,000 dilution group." (PMID 41392981, 2025). "The present analysis showed, for the first time, that the anti-tumor effect of fisetin was mediated mainly through modulation of multiple signaling pathways and via activation of CDKN1A, SEMA3E, GADD45B and GADD45A and down-regulation of TOP2A, KIF20A, CCNB2 and CCNB1 genes." (PMID 28052097, 2017). "Similarly, KIF20A overexpression did not change the CSC frequency in vivo or tumor growth." (PMID 41392981, 2025). "Furthermore, we explored the cellular effects of KIF20A and its upstream transcription factor GATA2 on cell growth and apoptosis in an HBV-infected HCC cell line, aiming to elucidate the intricate relationship between KIF20A and HBV infection in HCC tumor progression." (PMID 39624268, 2024). "Results showed that IFI27, KIF20A, KLK10 and TOP2A were significantly upregulated in tumor cells relative to normal cells, whereas SPINK7 showed no differential expression." (PMID 41008826, 2025). "Unlike the three GRGs above, the potential role of KIF20A and STC2 in tumor development, progression and prognosis has been widely studied." (PMID 35123420, 2022). "KIF20A was both transcriptionally and translationally upregulated in NPC cell lines and clinical tumor specimens, in comparison with noncancerous nasopharyngeal epithelial cells and tissues." (PMID 28081138, 2017).
cancer (112 papers, 2011 to 2026). A tumor composed of atypical neoplastic, often pleomorphic cells that invade other tissues. "We identified several proteins with high interaction scores (Cna2, Kif20a, Kif11, Cdk1, and Cdc20) that are closely associated with various cancers." (PMID 39596644, 2024). "This includes the potential for cancer cells to activate compensatory pathways or mutations in KIF20A that reduce the efficacy of targeted agents." (PMID 39272816, 2024). "This burgeoning body of evidence underlines the necessity for continued exploration of KIF20A in cancer immunotherapy." (PMID 39272816, 2024). "Overexpression of KIF20A has been associated with aggressive behavior and poor prognosis in cancer patients, and inhibiting KIF20A expression has been shown to reduce cancer cell proliferation and induce cell death in vitro and in animal models." (PMID 37310408, 2023). "The overexpression of KIF20A is linked to the onset, progression, and prognosis of different cancers." (PMID 35574421, 2022). "We have recently identified KIF20A, a mitotic kinesin previously implicated in cytokinesis regulation in cancer cells, with a crucial role in balancing symmetric vs. asymmetric NPC divisions during cerebral cortical development." (PMID 33976373, 2021). "With regard to that, further studies have confirmed that high expression of KIF20A is strongly associated with aggressive phenotypes of cancer." (PMID 31565099, 2019). "However, research has revealed that EZH2 and KIF20A are strongly linked to the growth and prognosis of cancer and coexist in many prognostic indicators, offering crucial hints for further investigation." (PMID 40465746, 2025). "This knowledge is essential for refining these compounds to maximize their therapeutic potential, especially in targeting cancers associated with overactive KIF20A, which could lead to more effective treatments for such malignancies." (PMID 39272816, 2024). "Besides, there were plenty of studied predicted that KIF20A was highly expressed in cancers and associated with poor OS based in public data platforms, for example, TCGA, GEO." (PMID 36798768, 2023). "However, further research is needed to fully understand the underlying mechanisms of KIF20A in cancer and to develop effective therapeutic strategies targeting this protein." (PMID 37310408, 2023). "Besides, Moreover, changes in the KIF20A genome were also associated with cancers (data was from cBioPortal)." (PMID 36798768, 2023). "KIF20A, a member of the kinesin family, plays a critical role in cytokinesis, and more importantly, it has been associated with the development and progression of various kinds of human cancers." (PMID 33736645, 2021). "KIF20A is associated with drug resistance and the clinical prognosis in diverse cancers." (PMID 33784984, 2021). "However, further studies to investigate the underlying mechanisms of KIF20A-mediated carcinogenesis and cancer progression in PCa are needed." (PMID 31565099, 2019). "In human cancers, KIF20A shows low mutation rate based on available TCGA database, which is consistent with the essential role of KIF20A in cell divisions of NPCs or other stem/progenitor cells (germline knockout of the Kif20a leads to embryonic/perinatal lethality)." (PMID 33976373, 2021). "Pan‐cancer co‐expression analysis by the ENCORI database revealed that there was a positive correlation between KIF20A and BUB1 mRNA levels in CC tissues." (PMID 40914946, 2026). "The attenuation of BCSC self-renewal upon KIF20A depletion prompted us to assess its effect on cancer stem cell (CSC) frequency using the extreme limiting dilution assay." (PMID 41392981, 2025). "In fact, KIF20A is overexpressed in all the cancers present in the Gene Expression Profile Interactive Analysis (GEPIA) server, including COAD, PAAD, PRAD, and TNBC." (PMID 40176904, 2025).